FBXO4 (F-box protein 4)
Description:
Substrate recognition component of a SCF (SKP1-CUL1-F-box protein) E3 ubiquitin-protein ligase complex that mediates the ubiquitination and subsequent proteasomal degradation of target proteins. Promotes ubiquitination of cyclin-D1 (CCND1) and its subsequent proteasomal degradation. However, it does not act as a major regulator of CCND1 stability during the G1/S transition (By similarity). Recognizes TERF1 and promotes its ubiquitination together with UBE2D1. Promotes ubiquitination of FXR1 following phosphorylation of FXR1 by GSK3B, leading to FXR1 degradation by the proteasome.
Synonyms: FBX4
Tractability: PROTAC: ubiquitination databases record sites on it.
Gene: Protein-coding gene on chromosome 5 (41,925,210 to 41,941,743, forward strand). Ensembl gene ENSG00000151876.
Subcellular location: Cytoplasm
Subcellular location (Human Protein Atlas): Nucleoplasm
Pathways (Reactome):
Metabolism of proteins: Association of TriC/CCT with target proteins during biosynthesis; Neddylation
Immune System: Antigen processing: Ubiquitination & Proteasome degradation
Gene Ontology:
Molecular function: protein binding; protein homodimerization activity; ubiquitin-like ligase-substrate adaptor activity; ubiquitin-protein transferase activity; ubiquitin protein ligase activity
Biological process: positive regulation of protein ubiquitination; positive regulation of telomere maintenance via telomerase; protein polyubiquitination; protein ubiquitination; regulation of protein stability; SCF-dependent proteasomal ubiquitin-dependent protein catabolic process; regulation of DNA damage checkpoint
Cellular component: cytoplasm; SCF ubiquitin ligase complex; ubiquitin ligase complex; cytosol
Genetic constraint (gnomAD): Loss-of-function variants: 31 observed, 35.24 expected, observed/expected ratio (o/e) 0.88, 90% interval 0.66 to 1.19. The upper end of that interval is the gene's LOEUF score, 1.19, which puts it in group 5 of 6, group 1 being the genes least tolerant of losing a copy. Missense variants: 412 observed, 424.77 expected, observed/expected ratio (o/e) 0.97, 90% interval 0.89 to 1.05. Synonymous variants: 173 observed, 150.08 expected, observed/expected ratio (o/e) 1.15, 90% interval 1.02 to 1.31.
Homologues: Orthologues: chimpanzee FBXO4 (99% identical), macaque RIMOC1 (99% identical), dog FBXO4 (90% identical), rabbit FBXO4 (90% identical), pig FBXO4 (90% identical), rat Fbxo4 (88% identical), mouse Fbxo4 (88% identical), guinea pig FBXO4 (76% identical), tropical clawed frog fbxo4 (55% identical), zebrafish fbxo4 (40% identical).
Diseases named in the same sentence as FBXO4 in open-access papers:
FBXO4 is named in the same sentence as 38 diseases in open-access papers, as found by Europe PMC text mining. Sharing a sentence is not in itself a finding about the gene and the disease. The quoted sentences say what the papers report.
melanoma (6 papers, 2016 to 2022). A malignant, usually aggressive tumor composed of atypical, neoplastic melanocytes. "Collectively, these data suggest loss of hnRNPK or overexpress of Fbxo4 is sufficient to significantly suppress spontaneous lung colonization of B16F10 melanoma cells in vivo." (PMID 36329064, 2022). "Consistent with observations in Fbxo4-deficient MEFs, Fbxo4-I377M melanoma cell lines exhibited increased capacity for invasion relative to melanoma cell lines with Fbxo4;wt this invasive phenotype was dependent on expression of hnRNPK." (PMID 36329064, 2022). "Consistently, our mechanistic studies demonstrate that loss of Fbxo4 increases cell motility, cell invasion, and melanoma metastasis in an hnRNPK- and c-Myc-dependent manner." (PMID 36329064, 2022). "Fbxo4 inactivating mutations occur in ~10% of melanoma and a common mutation is I377M, inhibiting substrate binding." (PMID 36329064, 2022). "FBXO4 is generally identified as a tumor suppressor, FBXO4-deficient mice will develop highly aggressive melanomas, as well as lymphomas, histolytic sarcomas, mammary and hepatocellular carcinomas." (PMID 30341246, 2019). "Dysregulation of the cyclin D1/CDK4 pathway occurs in a majority of melanomas and increased cyclin D1/CDK4 activity (e.g. loss of p16Ink4A or Fbxo4) cooperates with BrafV600E to drive melanoma." (PMID 27977682, 2016). "Therefore, the inactivation or loss of Fbxo4 that occurs in melanoma and esophageal cancer unleashes cytoplasmic hnRNPK activity, unmasking malignant function though dysregulated translation of multiple mRNA targets that promote tumor progression." (PMID 36329064, 2022). "In addition to mutations, Fbxo4 protein loss is observed at high frequency in melanoma and esophageal cancers." (PMID 36329064, 2022). "In addition, loss of Fbxo4 enhances the development of aggressive melanoma in a BrafV600E/+ mouse model." (PMID 35565262, 2022). "Moreover, melanoma cells with Fbxo4I377M mutation also exhibit increased Fxr1 levels, consistent with Fbxo4-dependent regulation of Fxr1 in normal cells, and the disruption of this pathway in human cancers." (PMID 29142209, 2017). "We further compared three melanoma cell lines bearing Fbxo4 mutations Lu1205I377M-Fbxo4, WM739BI377M-Fbxo4, WM3918I377M-Fbxo4, two cell lines harboring FBXO4wt (WM983Bwt-Fbxo4, WM35wt-Fbxo4) versus primary human melanocytes (PHM80 and PHM90)." (PMID 36329064, 2022). "Comparison of melanoma resection samples with normal human skin samples revealed increased c-Myc with reduced αB-Crystallin and Fbxo4." (PMID 36329064, 2022). "In accordance, Fbxo4 knockout mice can photocopy its tumor suppressor activities in BrafV600E/+ melanoma, and esophageal and forestomach papilloma models, further confirming that Fbxo4 has tumor suppressor activities." (PMID 35565262, 2022). "proved that FBXO4 deficiency induces melanoma in BRAF‐activated mice, with the expression of cyclin D accumulated in the nucleus of melanoma cells in the presence of FBXO4 inactivation." (PMID 28544818, 2017). "Several studies found that Fbxo4 expression is downregulated in hepatocellular carcinoma (HCC) and HNSCC tissues comparing to their normal counterparts, and Fbxo4 loss of function mutations are revealed in human ESCC tissues and melanoma cells." (PMID 35565262, 2022). "For example, the presence of Fbxo4 mutations disrupts its ability to dimerize and to form the SCF complex in ESCC tumor specimens, and the existence of a substrate-binding deficient Fbxo4, Isoleucine (Ile)-377 to methionine mutant, in melanoma cells." (PMID 35565262, 2022). "Deletion of both Perk alleles effectively inhibited BrafV600E-dependent melanoma in the setting of Fbxo4-deficiency, while deletion of one allele of Perk (Perk+/-) was not sufficient to either inhibit or accelerate melanoma genesis." (PMID 27977682, 2016).
melanoma (continued). "The genetic manipulation of Fbxo4 successfully alters the stability of cyclin D1 protein, which is evidenced by the accumulation of cyclin D1 protein in human ESCC tissues and melanoma cells with defective Fbxo4." (PMID 35565262, 2022). "Typically, BrafV600E-dependent melanoma can be achieved by deletion or inactivation of known tumor suppressors, such as PTEN, p16Ink4A, Fbxo4." (PMID 27977682, 2016).
breast carcinoma (4 papers, 2017 to 2023). "FBXO4 overexpression decreased EMT in metastatic breast cancer cells with a loss of fibronectin, vimentin, and ZEB1." (PMID 29137327, 2017). "Moreover, low Fbxo4 levels are associated with poor prognosis in patients with breast cancer." (PMID 35565262, 2022). "FBXO4 protein affects the activation or inhibition of downstream signaling in metastatic breast cancer cells." (PMID 29137327, 2017). "The transcriptional level of FBXO4 was significantly higher in the luminal subtype breast cancer cell than in the basal subtype." (PMID 29137327, 2017). "Increasing evidence shows that FBXO proteins are involved in tumor development as either pro- or anti-oncogenic factors; for example, FBXO4 inhibits breast cancer development by interacting with intercellular adhesion molecule-1 (ICAM-1), promoting its ubiquitination, and decreasing its stability." (PMID 37348029, 2023). "Moreover, elevated Fbxo4 levels are correlated with longer survival in comparison to those with low Fbxo4 expression in breast cancer patients." (PMID 35565262, 2022). "Four miRNAs were found by prediction analysis, all of which were downregulated by the ERK inhibitor U0126 in metastatic or non-metastatic breast cancer cells; particularly, the level of FBXO4 was significantly decreased in cells transfected with miR340." (PMID 29137327, 2017). "Additionally, we confirmed that knockdown of FBXO4 alone or co-knockdown of FBXO4 and ICAM-1 reversed these effects in non-metastatic breast cancer cells." (PMID 29137327, 2017).
esophageal squamous cell carcinoma (4 papers, 2017 to 2025). Esophageal squamous cell carcinoma (ESCC) is a type of esophageal carcinoma (EC) that can affect any part of the esophagus, but is usually located in the upper or middle third. "The screening of human esophageal squamous cell carcinoma (ESCC) tissues identified the existence of Fbxo4 mutations, such as S8R, S12L, P13S, L23Q, and G30N in D domain, and P76T mutation in F-box domain, leading to loss of function of Fbxo4." (PMID 35565262, 2022). "A subset of esophageal squamous cell carcinoma harbors dysregulated Fbxo4- cyclin D1 axis." (PMID 30899002, 2019). "The dysregulation of Fbxo4-cyclin D1 axis occurs at high frequency in esophageal squamous cell carcinoma (ESCC), where it promotes ESCC development and progression." (PMID 30899002, 2019). "Furthermore, studies have demonstrated that combination therapies can overcome resistance to the cyclin-dependent kinase 4/6 (CDK4/6) inhibitor palbociclib in esophageal squamous cell carcinoma (ESCC) with dysregulation of the FBXO4-cyclin D1 axis." (PMID 40534867, 2025).
esophageal cancer (3 papers, 2008 to 2022). A primary or metastatic malignant neoplasm involving the esophagus. "In esophageal cancer, dysregulation of the FBXO4-cyclin D1-RB axis promotes glutamine addiction and highlights a therapeutic weakness for overcoming CDK4/6 inhibitor resistance." (PMID 35877430, 2022).
head and neck squamous cell carcinoma (3 papers, 2017 to 2023). A squamous cell carcinoma that arises from any of the following anatomic sites: lip and oral cavity, nasal cavity, paranasal sinuses, pharynx, larynx, and salivary glands. "Degradation of FXR1mediated by Fbxo4 inhibits tumorigenesis in head and neck squamous cell carcinoma, meanwhile, FXR1regulates Fbxo4 expression through inhibition of protein translation in the feedback." (PMID 30691465, 2019). "Critically, in head and neck squamous cell carcinoma, Fxr1 overexpression correlates with reduced Fbxo4 levels in the absence of mutations or loss of mRNA, suggesting the potential for feedback regulation." (PMID 29142209, 2017).
hepatocellular carcinoma (3 papers, 2019 to 2022). A malignant tumor that arises from hepatocytes. "Fbxo4−/− or Fbxo4+/− mice spontaneously develop multiple tumors—including lymphoma, histiocytic sarcoma, and, less frequently, mammary and hepatocellular carcinomas —as well as show an increased susceptibility to the N-nitrosomethylbenzylamine-induced development of papilloma." (PMID 32429232, 2020).
glioma (2 papers, 2021 to 2025). A benign or malignant brain and spinal cord tumor that arises from glial cells (astrocytes, oligodendrocytes, ependymal cells). "Using the Gene Expression Profile Interaction Analysis (GEPIA) server, we identified a gene, FBXO4, that was independently associated with overall survival in low-grade glioma patients." (PMID 40130175, 2025). "Our results revealed that, at the RNA level glioma cell lines expressed higher levels of FBXO4 than did normal human astrocytic brain cells, especially the U87 and U251 cell lines." (PMID 40130175, 2025). "Additionally, we experimentally validated FBXO4, a top candidate gene, for its role in glioma cell proliferation and immune modulation." (PMID 40130175, 2025).
lung carcinoma (2 papers, 2022 to 2023). "FBXO4 is recently identified as an E3 ubiquitin ligase to interact and promote Mcl-1 ubiquitination and degradation in lung cancer." (PMID 35301297, 2022).
metastatic melanoma (2 papers, 2016 to 2020). A melanoma that has spread from its primary site to another anatomic site. "Loss of Fbxo4 also increases the aggressiveness of BRAFV600E-dependent metastatic melanoma in mice, highlighting the importance of FBXO4 as a suppressor of tumor progression." (PMID 32429232, 2020). "We have previously demonstrated that inactivation of Fbxo4 in the BrafV600ECA/+ background triggers cyclin D1-dependent, metastatic melanoma." (PMID 27977682, 2016).
papilloma (2 papers, 2017 to 2020). A benign epithelial neoplasm that projects above the surrounding epithelial surface and consists of villous or arborescent outgrowths of fibrovascular stroma. "IHC revealed elevated Fxr1 in normal tissues from Fbxo4−/− and + /− mice relative to that in Fbxo4 + / + mice; an obvious elevation of Fxr1 was noted in papilloma of Fbxo4 + /− and −/− mice compared to that in + / + mice." (PMID 29142209, 2017).
prostate carcinoma (2 papers, 2022 to 2023). A carcinoma that arises from epithelial cells of the prostate gland. "In prostate cancer cells, FXR1 negatively regulated FBXO4 transcripts via direct association with its 3’UTR and promoted mRNA degradation." (PMID 36498797, 2022).
cervical cancer (1 paper, 2025). A primary or metastatic malignant neoplasm involving the cervix. "Upon validation of these results in cervical cancer-derived cell lines, we found that the combined knockdown of both F-box protein 4 (FBXO4) and E6AP leads to a dramatic increase in the levels of endogenous HPV-18E6 oncoprotein." (PMID 39688415, 2025). "Upon validation of the interaction of 18E6 with these ubiquitin ligases in cervical cancer-derived cell lines, we found that the knockdown of ubiquitin ligase F-box protein 4 (FBXO4), together with E6AP knockdown, leads to a dramatic increase in the levels of endogenous HPV-18E6 oncoprotein." (PMID 39688415, 2025). "This study, for the first time, identifies a novel ubiquitin ligase, FBXO4 that targets the degradation of HPV E6 oncoprotein in the absence of E6AP in cervical cancer-derived cell lines." (PMID 39688415, 2025).
metastatic cancer (1 paper, 2017). A carcinoma which has spread from the original site of growth to another anatomic site. "Notably, FBXO4 shows specificity towards ICAM-1 and may have different ubiquitin-dependent regulatory roles such as the suppression of metastatic cancer progression via diverse pathways." (PMID 29137327, 2017).
non-small cell lung carcinoma (1 paper, 2022). A group of at least three distinct histological types of lung cancer, including non-small cell squamous cell carcinoma, adenocarcinoma, and large cell carcinoma. "In non-small cell lung cancer (NSCLC) cells, Fbxo4 protein levels are reversely correlated with Mcl-1 expression." (PMID 35565262, 2022).
Sepsis (1 paper, 2025). Sepsis is defined as life-threatening organ dysfunction caused by a dysregulated host response to infection.
tumor (16 papers, 2008 to 2025). "Clinicopathologically, the expression of Fbxo4 is associated with patients’ prognosis depending on different tumor types." (PMID 35565262, 2022). "In addition, other mutations in the FBXO4 gene have also been discovered in tumor tissues from the TCGA PanCancer Atlas Studies, and in cells from the Cancer Cell Line Encyclopedia on the cBioportal website." (PMID 35565262, 2022). "FBXO4 knockdown predominantly rescued the tumor-suppressive phenotype in FXR1-deficient cells." (PMID 36498797, 2022). "In the present study, we found that miR340 is a potential tumor suppressor associated with FBXO4." (PMID 29137327, 2017). "It is noteworthy, that all established relationships between SCFFbxo4 and its substrates, phenotypically reflect a tumor suppressor (Fbxo4)–oncogene (substrate) interplay." (PMID 36329064, 2022). "As an E3 ubiquitin ligase of cyclin D1, Fbxo4 regulates cell cycle progression in both normal and tumor cells." (PMID 35565262, 2022). "Consistently, different Fbxo4 isoforms have also been elucidated by analyzing normal human liver/esophagus tissues and their relevant tumor cells." (PMID 35565262, 2022). "All well-known Fbxo4 substrates can participate in a variety of biological processes related to tumor development and progression, defining Fbxo4 as a tumor suppressor." (PMID 35565262, 2022). "Overexpression of Fbxo4 not only reduces the size and weight of primary tumor xenografts, but also compromises the formation of metastatic tumors." (PMID 35565262, 2022). "Tumor suppressive functions of Fbxo4 are only partially cyclin D1-dependent, highlighting the existence of key unidentified, pro-tumorigenic targets." (PMID 36329064, 2022). "Here we demonstrate that pro-tumorigenic activities of cytoplasmic hnRNPK are checked by the tumor suppressive function of Fbxo4." (PMID 36329064, 2022). "Not surprisingly, the observations from transgenic mice also confirm the tumor suppressor activities of Fbxo4." (PMID 35565262, 2022). "Biologically, Fbxo4 regulates cell cycle progression, DNA damage response, tumor metabolism, cellular senescence, metastasis and tumor cells’ response to chemotherapeutic compounds." (PMID 35565262, 2022). "Together these observations demonstrate that according to the expected tumor suppressor nature of Fbxo4, SCFFbxo4 functions as a limiting factor for hnRNPK-mediated oncogenic translation." (PMID 36329064, 2022). "Although similar total Fbxo4 protein was presented in sample #7, low phospho-Ser12 Fbxo4 was observed, suggesting reduced SCFFbxo4 E3 ligase activity in this tumour." (PMID 29142209, 2017). "In this manner, the modest increase of Fxr1 expression will have a profound impact on tumorigenesis by virtue of its capacity to suppress a documented tumour suppressor, Fbxo4, resulting in overexpression of pro-neoplastic SCFFbxo4 targets." (PMID 29142209, 2017). "Fbxo4 is a tumour suppressor, and its tumour suppressing activity has been linked to the dysregulation of cyclin D1 proteolysis." (PMID 29142209, 2017). "The Fbxo4 tumour suppressor is a component of an Skp1-Cul1-F-box E3 ligase for which two substrates are known." (PMID 29142209, 2017). "Elucidation of the regulatory relationships between Fbxo4 and RBPs will provide key insights into the regulation of cell homeostasis by Fbxo4, its role as a tumor suppressor and hopefully contribute to the identification of new therapeutic opportunities for cancer treatments." (PMID 36329064, 2022). "As such, their E3 ubiquitin ligase, Fbxo4, is defined as a tumor suppressor." (PMID 35565262, 2022).